PDZK1 (PDZ domain containing 1)
Diseases named in the same sentence as PDZK1 in open-access papers (continued):
Sharing a sentence is not in itself a finding about the gene and the disease.
esophageal cancer (1 paper, 2024). A primary or metastatic malignant neoplasm involving the esophagus. "Previous studies have revealed that PDZK1 is an oncogene for tumorigenesis and the development of papillary thyroid cancer and esophageal cancer." (PMID 38532426, 2024).
gastric tumors (1 paper, 2023). "In probing the potential clinical relevance of this oncogenic PTEN mechanism, we obtained transcriptomic evidence suggesting that WNT/β-catenin activity is indeed elevated in gastric tumors with increased PTEN C-tail phosphorylation due to PDZK1 insufficiency." (PMID 37225693, 2023).
inflammatory diarrhea (1 paper, 2012). An diarrhea (disease) involving a pathogenic inflammatory response in the intestinal mucosa. "Inflammation-induced PDZK1 downregulation may therefore be a contributory factor in the pathogenesis of inflammatory diarrhea in IBD." (PMID 22848392, 2012).
intrahepatic cholestasis (1 paper, 2017). A cholestasis characterized by impairment of the bile flow caused by obstruction located in the liver. "Administrating rats with CBS (50 or 150 mg/kg) notably increased PDZK1 mRNA expression compared with that of EE-induced intrahepatic cholestasis rats." (PMID 28133487, 2017). "The mRNA expression of PDZK1, as detected by RT-qPCR, significantly decreased in EE-induced intrahepatic cholestasis rats compared with that in normal rats." (PMID 28133487, 2017). "Since CBS upregulated the mRNA and protein expression levels of PDZK1 in EE-induced intrahepatic cholestasis rats measured by RT-PCR, western blot, and immunohistochemistry analysis, the bile transport abilities of MRP2 and BCRP were recovered, respectively." (PMID 28133487, 2017). "When treated with CBS, cumulative biliary excretions and mRNA and protein expressions of PDZK1 were significantly increased in intrahepatic cholestasis rats." (PMID 28133487, 2017). "At the same time, the expression of PDZK1 in the liver of intrahepatic cholestasis rats was also measured to preliminarily explore its role in biliary transport." (PMID 28133487, 2017). "This study demonstrated that CBS exerted a beneficial effect on EE-induced intrahepatic cholestasis rats by restoring biliary transport function, which may result from the upregulation of PDZK1 expression." (PMID 28133487, 2017). "Thus, CBS was involved in recovering PDZK1 expression in EE-induced intrahepatic cholestasis rats." (PMID 28133487, 2017). "In this study, we analyzed the possible modulation of PDZK1 in EE-induced intrahepatic cholestasis rats and subsequently explored the potential function of CBS in PDZK1 expression to clarify the choleretic mechanism." (PMID 28133487, 2017). "The possible regulations of PDZK1 on the localization and function of MRP2 and BCRP may play an importance role in restoring the biliary transport function of EE-induced intrahepatic cholestasis rats." (PMID 28133487, 2017). "Hence, we postulated that CBS relieved intrahepatic cholestasis by enhancing the functions of MRP2 and BCRP via the PDZK1 pathway." (PMID 28133487, 2017). "In view of the regulatory abilities of PDZK1 and the regulation of CBS on BCRP and MRP2, we speculated that PDZK1 might participate in CBS-regulated bile salt delivering and play an important role in restoring biliary transport function in EE-induced intrahepatic cholestasis." (PMID 28133487, 2017).
Myocardial fibrosis (1 paper, 2009). "We previously did not observe substantial coronary arterial occlusion nor myocardial fibrosis in PDZK1/apoE dKO mice fed a Western diet for three months." (PMID 19956623, 2009).
peritonitis (1 paper, 2018). Inflammation of the peritoneum (tissue that lines the abdominal wall and covers most of the organs in the abdomen). "Leukocyte PDZK1 deficiency in otherwise wild type mice did result in increased sensitivity of macrophages to tunicamycin-induced apoptosis in a peritonitis model." (PMID 30246067, 2018).
rectal cancer (1 paper, 2024). A primary or metastatic malignant neoplasm that affects the rectum. "Therefore, further research is needed to explore the effect of PDZK1 expression on rectal cancer risk." (PMID 39011473, 2024). "The leave-one-out analyses found that rs1471633 in the PDZK1 gene had great possibility to drive the causal association between SUA and rectal cancer risk in overall population, males and females." (PMID 39011473, 2024).
renal papillary cell carcinoma (1 paper, 2020). "PDZK1, SLC22A2, and SLC44A4 have also a prognostic value for patients with renal papillary cell carcinoma." (PMID 32599841, 2020).
seborrheic keratosis (1 paper, 2021). A common benign skin neoplasm usually affecting older individuals. "Staining intensity with an anti-ABCG2 antibody was stronger in lesional epidermis compared to normal epidermis of seborrheic keratosis showing increased PDZK1 staining intensity." (PMID 34830382, 2021). "Stronger staining intensities with anti-PDZK1 and anti-ABCG2 antibodies in lesional epidermis of seborrheic keratosis also supported clinical implications of their relations." (PMID 34830382, 2021).
trigonocephaly (1 paper, 2017). "Likewise, none of the genes duplicated in patient 6 (NBPF20, GPR89A, PDZK1, CD160, RNF115) are known to cause trigonocephaly." (PMID 28724436, 2017).
tumor (21 papers, 2007 to 2026). "Taken together, the results of our study show that high expression of PDZK1 is associated with lymph node metastasis, degree of tumor differentiation, and clinical stage of HCC." (PMID 38532426, 2024). "Uric acid may cause tumor immune response, so PDZK1 may also be related to tumor immune progress." (PMID 36420358, 2022). "Pharmacological ULK1 activation with LYN-1604 restores sunitinib sensitivity in PDZK1-knockdown cells and synergizes with sunitinib in xenograft models, reducing tumor growth and LD accumulation." (PMID 41698049, 2026). "We first investigated PDZK1 levels in tumour tissue and normal tissue of PCa patients to study the potential role of PDZK1 in different tissues." (PMID 39819421, 2025). "Increasing evidence suggests that PDZK1 plays a role in inhibiting tumor progression and enhancing sensitivity to chemotherapeutic agents, highlighting its potential as a promising therapeutic target." (PMID 39819421, 2025). "In conclusion, this study provides the first evidence of the tumour-suppressing role of PDZK1 in TNBC." (PMID 38604999, 2024). "This work established that PDZK1 plays a tumour-suppressing role in TNBC by inhibiting EGFR signalling." (PMID 38604999, 2024). "PDZK1 participates in tumour development by interacting with multiple kinds of proteins, including multidrug resistance-associated protein 2 (MRP2), and regulating their activities." (PMID 38604999, 2024). "In these experiments, too, PDZK1 knockdown was found to significantly inhibit tumor cell migration and invasion in MHCC-97H cells, while overexpression of PDZK1 promoted the migration and invasion of Huh7 cells." (PMID 38532426, 2024). "These include the ubiquitin-conjugating enzyme E2C (UBE2C), the so-called “outer dense fibers of sperm tail 3B” (ODF3B), which is expressed in many tumor types, as well as the PDZ domain-containing protein 1 (PDZK1)." (PMID 39062119, 2024). "The PDZK1 level in HCC tissues was closely associated with lymph node metastasis, the degree of tumor differentiation, and clinical stage." (PMID 38532426, 2024). "The results showed that erlotinib more effectively suppressed tumour proliferation in vivo when PDZK1 was overexpressed." (PMID 38604999, 2024). "GT3-INCP/GATA3 bound to common cis regulatory elements and upregulated the expression of the tumor-promoting and estrogen-regulated BC susceptibility/risk genes MYB and PDZK1." (PMID 36856111, 2023). "The tumor volume of PDZK1 overexpression group are increased, and treat with allopurinol, the tumor volume is decreased." (PMID 36420358, 2022). "To study the relationship between the PDZK1 gene and the tumor microenvironment, we used single-sample GSEA to analyze the possible immune cell infiltration in the samples from the TCGA-LIHC database." (PMID 36052278, 2022). "Below, we discuss the potential effects of PDZK1 on gene signaling pathways and the tumor microenvironment." (PMID 36052278, 2022). "Ki67 result showed that after treatment with allopurinol, the proliferation of tumor was more reduced compare with PDZK1 overexpression group." (PMID 36420358, 2022). "The tumor volume of PDZK1 overexpression group are increased and after treat with allopurinol the tumor volume is decreased." (PMID 36420358, 2022). "High PDZK1 protein expression was classified as tumours with a staining intensity >2, and low expression classified as tumours with a staining intensity ≤2." (PMID 23547718, 2013). "tumour tissue exhibited significantly lower levels of PDZK1 protein compared with normal tissue." (PMID 39819421, 2025). "Additionally, we observed that IMP treatment preserved tumor tissue structure, reduced Ki-67 expression, and increased PDZK1 expression in the tumor tissue." (PMID 39819421, 2025). "PDZK1 promotes tumor development by regulating the phosphorylation of AKT1." (PMID 38669103, 2024). "Taken together, these results suggested that PDZK1 is a novel tumour suppressor specific for TNBC." (PMID 38604999, 2024).
tumor (continued). "All these results are in agreement and imply that PDZK1 is a potential tumor promoter gene in HCC." (PMID 38532426, 2024). "Regulatory PDZK1 expression can affect the proliferation, migration, and apoptosis of HCC; uric acid may cause tumor immune response." (PMID 36420358, 2022). "PDZK1 expression correlated positively with low grade tumours (p = 0.010)." (PMID 23547718, 2013). "In addition, genes involved in cell differentiation and apoptosis (PDZK1) and genes encoding actin and actin-binding proteins (CNN1, ACTA2) were also downregulated in both types of tumor cells." (PMID 17389037, 2007). "Moreover, the PDZK1 protein level was negatively correlated with tumour volume." (PMID 38604999, 2024). "Indeed, low PDZK1 expression also correlated with LEF1 hyperactivity in this tumor type." (PMID 37225693, 2023). "Thus far, there are no reports concerning the effect of PDZK1 on the tumor microenvironment, and we reported for the first time that high expression of PDZK1 was associated with immunosuppression caused by increased TAMs and Treg cells." (PMID 36052278, 2022). "Further, the level of PDZK1 in HCC tissues was positively correlated with clinical stage, degree of differentiation of the tumor, and lymph node metastasis." (PMID 38532426, 2024). "PDZK1 is upregulated in HGG, predicts poor survival, and differentiates tumor grading in HGG patients." (PMID 38692010, 2024). "Surprisingly, multiple previously reported tumor suppressors of KIRC were found in these downregulated genes, including SOX6, DAPK1, PDZK1, TXNIP, DAB2IP, and CMTM4." (PMID 37737260, 2023). "PDZK1 is an HBV infection-related gene, which plays oncogenic roles, possibly due to enhancing PI3K-Akt, fatty acid usage in tumor cells and TAMs, and Treg-induced immunosuppression." (PMID 36052278, 2022). "A scoring technique was devised attributing a score of +1 to each poor prognostic marker exhibited on immunostaining of individual tumour cores (i.e., high ANLN, high PBK and low PDZK1)." (PMID 23547718, 2013). "To investigate whether PDZK1 overexpression could sensitise TNBC cells to erlotinib in vivo, we further observed the effects of erlotinib treatment on tumour xenografts overexpressing PDZK1." (PMID 38604999, 2024). "In non-TNBC cells, PDZK1 exerts a tumour-promoting effect by mediating the formation of the oestrogen receptor α (ERα)/EGFR/Src complex." (PMID 38604999, 2024). "At 100 mg/kg bw/day, BPAF resulted in the significant upregulation in gene expression of seven targets (GPER1, JNK, Akt, Fos, FOXO1, PDZK1, SRF), while the gene expression of the other 12 targets were not significantly changed compared to the SK-BR-3 bearing tumor control." (PMID 36497816, 2022).
cancer (18 papers, 2006 to 2025). A tumor composed of atypical neoplastic, often pleomorphic cells that invade other tissues. "Our analysis highlighted LINC00853, which was significantly upregulated in cancer tissues and implicated in promoting epithelial-mesenchymal transition via the MAP17/PDZK1/AKT pathway." (PMID 38586313, 2024). "RT-qPCR and Western blot found that PDZK1 in cancer tissues was up-regulated compared with para-cancer tissues, and PDZK1 in grade IV HGG patients was higher than in grade III HGG patients." (PMID 38692010, 2024). "Treatment of cells with fulvestrant significantly inhibits ER-α dependent IGF-1R, phospho-IRS-1 and PDZK1 pathways regulating cancer cell invasion, survival, metastasis, angiogenesis and proliferation." (PMID 29787591, 2018). "Another interesting protein is PDZK1, which has been proposed to serve as a functional regulator for the breast cancer resistance protein in the small intestine." (PMID 24844638, 2014). "The previous studies reported inconsistent expression levels of PDZK1 across different cancers." (PMID 39011473, 2024). "Aberrant PDZK1 expression has been observed in several kinds of cancers." (PMID 38532426, 2024). "At the same time, luteolin also promoted the expression of PDZ domain-containing 1 (PDZK1) and PDZ domain-containing 3 (PDZK2), which increased OCTN2 expression on cancer cell surfaces with enhanced transporter activity." (PMID 39061884, 2024). "This study found that PDZK1 was upregulated in cancer tissues of HGG patients, and patients with high PDZK1 expression had poor OS and PFS." (PMID 38692010, 2024). "As expected, cancer cluster-related genes ATF3, PDZK1, VTN and CXCL8 were highly expressed in CDRCC tissues, and patients with high expression of these genes had significantly poor prognosis (P<0.01)." (PMID 33162821, 2020). "While two genes, PDZK1 and MLLT11, were clearly relevant to cancer as both have been proposed as a candidate oncogenes in diverse haematological malignancies, 6 were more difficult to relate to cancer." (PMID 17060936, 2006). "We found that PDZK1 may be an ideal gene that is associated with HBV infection and is significantly differentially expressed in cancer and noncancer tissues." (PMID 36052278, 2022).
infection (4 papers, 2009 to 2022). The state of being infected such as from the introduction of a foreign agent such as serum, vaccine, antigenic substance or organism. "In these experiments VSVG-pseudoparticle infection levels were unchanged by PDZK1 knockdown, indicating that PDZK1 knockdown causes HCV-specific inhibition of viral entry." (PMID 20949066, 2010). "We identified 11 genes that were significantly altered after infection with both viruses, and among these genes, 6 were up-regulated after infection (Chl1, Nlrp12, Plk1, Cyfip2, Adamts3, and Pdzk1)." (PMID 30713529, 2018). "Effective knockdown of PDZK1 expression in Huh-7 cells was associated with a decreased susceptibility of these cells to infection with HCVcc and HCVpp, despite no discernable impact on total or surface levels of SR-BI protein." (PMID 20949066, 2010). "However, we found that PDZK1 knockdown was associated with a moderate yet significant reduction in the susceptibility of HepG2(N6)+CD81 cells to HCVcc (Jc1/Myc) infection (not shown)." (PMID 20949066, 2010). "Following infection of these cells with cell culture propagated HCV (HCVcc; JFH-1), HCV RNA levels were approximately 40% lower in the PDZK1-knockdown cell lines compared to cells that expressed a non-targeting shRNA control." (PMID 20949066, 2010).
inflammation (3 papers, 2012 to 2022). Aberrant reaction of the microcirculation characterized by movement of fluid and leukocytes from the blood into extravascular tissues. "In studies of intestinal inflammation, soluble uric acid increased the expression of PDZK1 and ABCG2." (PMID 36052278, 2022). "The present study investigates whether a causal relationship exists between the decreased PDZK1 expression and the NHE3 dysfunction in human and murine intestinal inflammation." (PMID 25271043, 2015). "Thus, NHE3 dysfunction despite normal NHE3 gene expression, but strongly reduced PDZK1 expression, is seen in both mouse models of chronic colonic inflammation." (PMID 22848392, 2012).
PDZK1 also shares sentences with these, for which no sentence is quoted: multiple myeloma (2 papers); osteoarthritis (2); renal carcinoma (2); arterial occlusion (1); coronary arterial atherosclerosis (1); esophageal adenocarcinoma (1); Infertility (1); inflammatory bowel disease (1); influenza (1); kidney (1); melasma (1); nephropathies (1); papillary thyroid cancer (1); psychiatric diseases (1); thyroid cancer (1); type 2 diabetes (1).